EGR1 (early growth response 1)
Diseases named in the same sentence as EGR1 in open-access papers (continued):
Sharing a sentence is not in itself a finding about the gene and the disease.
non-small cell lung carcinoma (27 papers, 2011 to 2024). A group of at least three distinct histological types of lung cancer, including non-small cell squamous cell carcinoma, adenocarcinoma, and large cell carcinoma. "Increased expression of EGR1 in human non-small cell lung carcinomas is associated with up-regulation of KRT18 and reduced lymph node metastasis." (PMID 30566430, 2018). "DUXAP8 was initially reported to promote non-small-cell lung cancer proliferation and invasion by epigenetically silencing EGR1 and RHOB." (PMID 32849765, 2020). "EGR1 has also been shown to decrease cell mobility and cell migration in non-small-cell lung cancer, thus, we assayed for the effects of EGR1 on cell mobility and migration in RMS cells using a wound healing assay." (PMID 29719592, 2018). "Recent studies indicated that DUXAP8 has a critical role in non-small-cell lung cancer cell proliferation and invasion by epigenetically silencing EGR1 and RHOB." (PMID 30367681, 2018). "At the same time, the curcumin-induced decrease of EGR-1 was validated, which was involved in the anti-proliferation and anti-migration activity of curcumin in non-small cell lung cancer (NSCLC) cells." (PMID 27529277, 2016). "The pseudogene DUXAP8 may act as an oncogene in non-small cell lung cancer, and it may play this role by silencing EGR1 and RHOB transcription via binding with EZH2 and LSD1." (PMID 33711952, 2021). "The same research group has demonstrated the anti-metastatic activity of curcumin in non-small cell lung cancer by decreasing the expression of early growth response protein 1 (EGR-1), and thereby reducing the adherens junctions and Wnt signaling pathway activity." (PMID 27834913, 2016). "In non-small cell lung cancer, EGR1 promoted ionizing radiation-induced EMT via the Egr-1/cathepsin L pathway." (PMID 36932397, 2023). "In non-small cell lung cancer, TGF-b1 has been found to decrease Egr-1-induced EMT of cancer cells, and high Egr-1 expression has been correlated with reduced EMT." (PMID 37046823, 2023). "In non-small cell lung cancer (NSCLC), DUXAP8 promotes tumor cell proliferation and invasion through epigenetically silencing Egr1 and RHOB." (PMID 34957112, 2021). "In non-small cell lung cancer (NSCLC), DUXAP8 promotes tumor cell proliferation and invasion through epigenetic silencing of Egr1 and RHOB." (PMID 34957112, 2021). "EGR1 promotes cell motility in various cancer cells including breast cancer, while inhibits EMT in non-small-cell lung cancer cells and bladder cancer cells." (PMID 31501409, 2019). "The pseudogene DUXAP8 was upregulated in non-small-cell Lung Cancer (NSCLC), and it can bind to EZH2 and LSD1 to repress the transcription of EGR1 and RHOB epigenetically, which was involved in the cell proliferation and invasion of NSCLC18." (PMID 29915327, 2018).
viral infection (25 papers, 2011 to 2025). "EGR1, a versatile transcription factor found in mammals, has been associated with various viral infections, including HSV-1, HIV, and EBV." (PMID 38601162, 2024). "EGR1, a zinc finger DNA-binding protein, has also been implicated in viral infection and immune response, and has shown link to I-IFN in recent studies." (PMID 38066591, 2023). "EGR1 expression is associated with many different viral infection types, including EV71, HIV, herpes simplex virus-1, and Kaposi’s sarcoma-associated herpesvirus." (PMID 30545363, 2018). "Early growth response gene-1 (EGR1) is a multifunctional transcription factor that is implicated in viral infection." (PMID 30319594, 2018). "EGR1 is also associated with multiple viral infections such as Venezuelan equine encephalitis virus (VEEV), Kaposi’s sarcoma-associated herpesvirus (KSHV), herpes simplex virus 1 (HSV-1), human polyomavirus JC virus (JCV), human immunodeficiency virus (HIV), and Epstein–Barr virus (EBV)." (PMID 36338037, 2022). "EGR1 has been associated with multiple viral infections such as VEEV (Venezuelan equine encephalitis virus), KSHV (Kaposi’s sarcoma-associated herpesvirus), HSV-1 (herpes simplex 1), JCV (human polyomavirus JC virus), HIV (human immunodeficiency virus) and EBV (Epstein–Barr virus)." (PMID 36338037, 2022). "Several studies indicate that EGR1 is linked to viral infection and immune response." (PMID 30319594, 2018). "EGR1 is a transcription factor that is mainly involved in the processes of tissue injury, immune responses, viral infection and tumor anti-angiogenic action." (PMID 40789964, 2025). "Our observations revealed similar results to other studies, underscoring the biological relevance and general importance of EGR1 in viral infections." (PMID 40789964, 2025). "EGR1 also plays roles in viral pathogenesis.During viral infections, EGR1 expression can facilitate either an antiviral or pro-viral cellular state, depending on the virus and the transcriptional events regulated by EGR1." (PMID 40789964, 2025). "EGR1’s activation during viral infections can regulate host proteins that degrade or misfold viral proteins, affecting viral particle assembly and replication." (PMID 39456924, 2024). "In the context of viral infections, EGR1 is quickly activated and can influence host–pathogen interactions by modulating the expression of genes involved in immune responses." (PMID 39456924, 2024). "The induction of EGR1 following viral infection stimulates multiple inflammatory factors (EGR2 and EGR4) and mediates host cell response to viruses." (PMID 37998351, 2023). "Members of the Early Growth Response family of transcription regulators (EGR1, 3, and 4) play an important role in the regulation of cellular responses to growth factors, DNA damage, and viral infection." (PMID 37998351, 2023). "Collectively, these results suggest that EGR1 induction following viral infection stimulates multiple inflammatory mediators." (PMID 35746681, 2022). "Here, we further elucidate the influence of EGR1 on the gene expression of inflammatory markers and apoptotic transcriptional machinery following viral infection." (PMID 35746681, 2022). "Here, we extend these studies to determine the impacts of EGR1 on gene expression following viral infection." (PMID 35746681, 2022). "Given the role of EGR1 in learning and memory, the potential impacts of EGR1 on the development of neurological sequelae following viral infections is especially of interest." (PMID 36338037, 2022). "EGR1 can be activated by a wide array of stimuli such as exposure to growth factors, cytokines, apoptosis, and various cellular stress states including viral infections by both DNA and RNA viruses." (PMID 36338037, 2022). "During viral infections, EGR1 expression can facilitate either an anti-viral or pro-viral cellular state, depending on the virus and the transcriptional events regulated by EGR1." (PMID 36338037, 2022).
viral infection (continued). "The increase in UL138 protein levels corresponded to increased EGR1 protein levels in the context of ΔUS22 virus infection." (PMID 31725811, 2019). "In two independent experiments, EGR1 precipitated 4-fold more site 1 and 2 sequence in the WT-virus infection relative to the IgG control." (PMID 31725811, 2019). "EGR1 can be upregulated upon viral infection by Epstein-Barr virus, mouse hepatitis virus (MHV), VEEV, EV71, rabies viruses and Japanese encephalitis virus infections." (PMID 30319594, 2018). "Egr-1 induction triggered by viral infection was determined by Western Blot analyses and immune-fluorescent microscopy." (PMID 25264522, 2013). "In this study we investigate the mechanisms controlling Egr-1 expression by viral infection and to understand its effects on viral life cycles." (PMID 25264522, 2013). "Additional experiments are required to determine the induction mechanisms of Egr-1 by viral infection." (PMID 21619646, 2011). "EGR1 can be activated by a wide array of stimuli (e.g., growth factors, cytokines) and various cellular stress states (e.g., viral infections (HSV-1 (herpes simplex 1), HIV (human immunodeficiency virus), EBV (Epstein–Barr virus)), acting either by the activation or suppression of virus infectivity." (PMID 40006985, 2025). "We next sought to assess whether EGR1 upregulation is limited to VEEV infection or if EGR1 is globally upregulated following viral infections in general." (PMID 35746681, 2022). "Future single-cell plus spatial sequencing technologies will provide a better understanding of EGR1 functions within the highly complex tissue of the brain in response to viral infections and unlock novel EGR1-dependent epigenetic markers as therapeutic targets for drug development." (PMID 36338037, 2022). "While EGR1 is most notably regarded for its involvement in brain development, plasticity, learning, and memory, it is actively being explored in other areas of research, including its role in viral infections." (PMID 35746681, 2022). "In this review, we examine EGR1 and its role(s) during viral infections." (PMID 36338037, 2022). "The role of EGR1 in viral infections has been explored by our lab and others." (PMID 35746681, 2022). "Notably, following viral infection, the levels of these transcripts (with the exception of EGR1) decreased at 1 dpi, with the levels of IFIT3 and ISG15 remaining significantly depleted at 3 dpi." (PMID 31451757, 2019). "EGR1, a multifunctional transcription factor, regulates diverse biological functions, including inflammation, apoptosis, differentiation, tumorigenesis, and even viral infections." (PMID 30545363, 2018). "Whether the difference of species or tissue tropism resulted in the different role of EGR1 in different virus infections remain unknown." (PMID 30319594, 2018). "Additional study using immunofluorescent microscopy showed that the Egr-1 signals coincided with the viral infection (GFP fluorescence from the recombinant virus), supporting the previous observation that Egr-1 was successfully stimulated after viral entry and transcription prior to the replication." (PMID 25264522, 2013). "Therefore from the host cell standpoint, viral infection can be considered as a stress and Egr1 is rapidly induced to turn on various cellular responses." (PMID 21619646, 2011). "Thus, the purpose of this review is to elucidate the roles of EGR1 during viral infections." (PMID 36338037, 2022). "Finally, EGR1 has been implicated to play a role in bacterial and viral infections; however, EGR1 and its role in viral infections have not previously been extensively reviewed." (PMID 36338037, 2022). "In addition, our preliminary studies revealed that Egr1 induced by viral infection was sufficient to interact with the ICP22 EBE during the lytic infection of SIRC and the over-expression of Egr-1 enhanced HSV-1 gene expression, replication, and release of infectious viruses (unpublished data)." (PMID 21619646, 2011).
viral infection (continued). "Finally, EGR1 may directly and/or indirectly impact gene expression after viral infection." (PMID 35746681, 2022). "Some studies conducted on viral infection, including KSHV have evidenced an enhanced level of Egr-1." (PMID 29207655, 2017). "At the early stages of virus infection i.e. at 4 hpi, we found up-regulation of immune genes like TNF-α3, EGR-1, IL6R, v-FOS, v-JUN." (PMID 21439068, 2011). "Interestingly, various studies have also drawn connections of EGR1 with necroptosis, CREB signaling, and viral infection." (PMID 33621216, 2021). "The significance of Egr-1 phosphorylation in the enhancement of DNA binding activity and transcription of target genes have been established but information related to the importance of Egr-1 phosphorylation in viral infection is lacking." (PMID 29207655, 2017). "Nevertheless, our preliminary data revealed that partial Egr-1 transcript was detected upon viral infection at 4°C or by UV-inactivated viruses (data not shown)." (PMID 25346859, 2014). "The experiment was first performed on 293 cells in which the Egr-1 was not induced by viral infection." (PMID 25264522, 2013). "Nevertheless, our preliminary data revealed partial Egr-1 transcript was detected upon viral infection at 4°C or by UV-inactivated viruses (data not shown)." (PMID 25264522, 2013). "Endogenous Egr-1 was present in uninfected 293HEK cells and the production was not stimulated by viral infection." (PMID 21619646, 2011). "The transcriptional regulator EGR1 is one of the Early growth response (EGR) family genes belonging to the group of Immediate-early genes (IEGs), which are stress-related genes responsible for the reaction to various external stimuli, including virus infections." (PMID 39407208, 2024). "Although the mechanism through which EGR-1 facilitates VACV replication remains elusive, we hypothesize that this cellular protein might exert a role in reprogramming gene expression in quiescent cells during viral infection." (PMID 29561772, 2018). "Therefore we investigated Egr-1 induction upon viral infection in the absence of viral replication by adding acyclovir (ACV) to block the viral DNA synthesis." (PMID 25264522, 2013). "Western blotting analysis showed that Egr-1 protein was not present in VERO cells but was induced upon infection and that its induction was enhanced with increased viral infection." (PMID 21619646, 2011).
diabetic nephropathy (24 papers, 2018 to 2026). "In the top 10 TFs of kidney, we found two TF markers including ID1, a transcriptional inhibitor that has been reported to drive dedifferentiation of kidney epithelial cells, and EGR1, an early growth response protein associated with diabetic kidney disease." (PMID 36762475, 2023). "Lipoxins reverse the progression of diabetic kidney disease with improved collagen deposition, mesangial expansion, and albuminuria through regulating the Egr-1 network." (PMID 35441585, 2022). "MEG3 facilitated inflammatory response and fibrosis by regulating the miR-181a/Egr-1/TLR4 axis in diabetic nephropathy." (PMID 34672863, 2021). "In kidney diseases, EGR1 was observed in the proximal tubule in response to hypoxic stimuli, and silencing of EGR1 could alleviate the injury in diabetic kidney disease and protect from renal inflammation and fibrosis." (PMID 35721209, 2022). "Based on the results of transcriptomics, the pathogenesis of diabetic kidney disease may involve 11 candidate differential genes: Egr1, Foxo3, Pik3r3, Fgf1, Sost, Wnt10a, Tgif2, Akt2, Mep1b, Col1a1, Apoe." (PMID 36249745, 2022). "However, MEG3 may play a pro-fibrosis role because it has been demonstrated to enhance fibrosis and inflammatory responses in diabetic nephropathy through the miR-181a/Egr1/TLR4 axis." (PMID 35890132, 2022). "Moreover, ChIP assays revealed that EGR1 was a transcriptional activator of NADPH oxidase 4, a key oxidative stress enzyme in diabetic kidney disease." (PMID 38166990, 2024). "It was reported that the lncRNA NEAT1/miR-34c/NLRP3 axis regulates pyroptosis activation and that the lncRNA MEG3/miR-181a/Egr-1/TLR4 signaling pathway promotes fibrosis and the inflammatory response, both of which mediate the progression of diabetic nephropathy." (PMID 34941711, 2021). "EGR1 is an important transcription factor that has been widely studied in the areas of oncology, neuropsychiatric disease and diabetic kidney disease (DKD), but it is not clear whether EGR1 is associated with hair growth." (PMID 35886025, 2022).
Insulin resistance (24 papers, 2013 to 2026). Increased resistance towards insulin, that is, diminished effectiveness of insulin in reducing blood glucose levels. "Among them, Egr1, Lcn2 and Socs3 were more abundant in liver and closely associated with insulin resistance." (PMID 40523992, 2025). "Egr1 gain-of-function in epididymal fat induces insulin resistance, while Egr1 loss-of-function improves the whole-body insulin sensitivity in diabetic mice." (PMID 32121305, 2020). "In our previous study, we identified EGR1 as a transcription factor of Ggpps, playing a vital role in the development of insulin resistance, which reminds us." (PMID 40412522, 2025). "For example, an animal study suggested the anti-diabetic effects of miR-92b-3p in T2D mice via regulation of the miR-92b-3p/EGR1 axis, which improved insulin resistance and pancreatic function." (PMID 40806035, 2025). "EGR1 promotes the progression of nonalcoholic fatty liver disease in patients with insulin resistance." (PMID 36716821, 2023). "Genes commonly upregulated in the IR-iPSCs when compared to each IS-iPSC group include EGR1 and MFGE8, which were previously associated with insulin resistance, as well as CD74, SEMA6B, SLFN13, TMEM151B, SLC22A17, and AGRN." (PMID 35987697, 2022). "Consistent with the data from previous studies 29, 30, the insulin tolerance test showed that Egr1-/- mice were protected from diet-induced insulin resistance." (PMID 32226550, 2020). "Consistently, our data and published results of other groups showed that Egr1-/- mice were protected from diet-induced insulin resistance." (PMID 32226550, 2020). "Since expressions of insulin-regulated genes are positively correlated with insulin sensitivity, down-regulation of HK2, EGR1, and CIDEC genes in this group possibly verify insulin resistance through deficiency of insulin signaling." (PMID 32831068, 2020). "Results showed down-regulation of insulin-responsive genes, HK2, EGR1, and CIDEC, which verify insulin resistance through deficiency of insulin signaling." (PMID 32831068, 2020). "The early growth responsive gene-1 (EGR1) is a zinc finger TF that plays an important role in metabolic processes like regulation of cholesterol biosynthesis genes in the liver or insulin resistance in type 2 diabetes." (PMID 31036066, 2019). "The link between Egr1 and insulin resistance is originally from the observation that Egr1 mRNA is highly increased in adipocytes from diabetic mice." (PMID 29607419, 2017). "Egr-1 mediated Egr-1/GGPPS/Erk1/2 pathway is one of the pathways involved in insulin resistance under hyperinsulinism condition observed in T2DM." (PMID 26966903, 2016). "Previous research has reported that D-gal regulated the ex pression of Lepr and Egr1 genes, which could reduce insulin sensitivity, and produce insulin resistance." (PMID 33952720, 2021). "The gene EGR1 enhances insulin resistance in T2D patients with chronic hyperinsulinemia." (PMID 30755828, 2019). "Egr-1 has a role in adipocyte insulin resistance through activation of the MAPK-ERK pathway." (PMID 31284541, 2019). "Many studies have also supported our results by demonstrating that hyperglycemia, hyperinsulinemia, insulin resistance, and hyperlipidemia often occur in D-galactose induced mice, which may be consequences of the high level of Egr1 expression and the decrease in palmitoleic acid in these mice." (PMID 26176541, 2015). "These cytokines upregulated EGR1 expression in hepatocytes, adipocytes and skeletal myocytes to transcriptionally activate its downstream targets LCN2 and SOCS3, thus aggravating insulin resistance in SH." (PMID 40523992, 2025). "White pitaya juice and purified peel betacyanins (PPBNs) improved insulin resistance through decreasing fibroblast growth factor-21 (FGF-21) expression and increasing level of FGF-21 related genes (Klb, FGFR2, Egr1 and cFos) in the liver." (PMID 28886195, 2017).